MTO1 (mitochondrial tRNA translation optimization 1)
Diseases named in the same sentence as MTO1 in open-access papers (continued):
Sharing a sentence is not in itself a finding about the gene and the disease.
heart failure (2 papers, 2017 to 2018). Inability of the heart to pump blood at an adequate rate to meet tissue metabolic requirements. "Presently, however, it is very unclear how TRMU mutations lead to liver disease while those in GTPBP3 and MTO1 lead to heart failure." (PMID 28732077, 2017). "Mutations in MTO1 or GTPBP3 impair the modification of the wobble uridine at position 5 of the pyrimidine ring and cause heart failure." (PMID 28732077, 2017). "A scenario in cardiomyocytes similar to that observed in fibroblasts could contribute importantly to the heart failure in MTO1 patients." (PMID 29348686, 2018).
Hepatic fibrosis (2 papers, 2019 to 2025). The presence of excessive fibrous connective tissue in the liver. "Additionally, circ-MTO1, derived from the MTO1 gene, has been found to suppress liver fibrosis by regulating the miR-17-5p/Smad7 axis." (PMID 40248098, 2025). "In hepatic fibrosis, circRNA_0071410 is indicated to be positively correlated with HSC activation and fibrogenesis, while circRNA MTO1 is considered to inhibit HSC activation and fibrogenesis." (PMID 31719209, 2019).
lung adenocarcinoma (2 papers, 2021 to 2023). A carcinoma that arises from the lung and is characterized by the presence of malignant glandular epithelial cells. "Circ-MTO1 has also been identified as a tumor suppressor that functions as part of the circ-MTO1/miR-17/QKI-5 feedback loop in inhibiting lung adenocarcinoma progression by inactivating the Notch signaling pathway." (PMID 36861443, 2023).
prostate carcinoma (2 papers, 2020 to 2022). A carcinoma that arises from epithelial cells of the prostate gland. "Another study exhibits that circ‐MTO1 is associated with decreased pathological T stage and N stage in patients with prostate cancer." (PMID 35478417, 2022). "Overexpression of circ-MTO1 in prostate cancer cells can inhibit cell viability and the expression of miR-17." (PMID 32904490, 2020). "circ‐MTO1 suppresses the growth and invasion of gastric, colorectal, and prostate cancer cells." (PMID 35478417, 2022). "Besides, circ‐MTO1 high expression is correlated with decreased pathological T/N stage, as well as longer disease‐free survival (DFS) and OS in prostate cancer patients." (PMID 35478417, 2022). "Furthermore, circ‐MTO1 is independently correlated with favorable DFS and OS in prostate cancer patients." (PMID 35478417, 2022).
Anxiety (1 paper, 2014). Intense feelings of nervousness, tension, or panic often arise in response to interpersonal stresses. "In the modified Hole Board test, Mto1 mice showed increased horizontal locomotor activity and reduced anxiety-related behaviour, but the significance of this finding remains unclear and it has no obvious correlate in patients." (PMID 25506927, 2014).
Arrhythmia (1 paper, 2014). Any cardiac rhythm other than the normal sinus rhythm. "Accordingly, there may be much milder affected Mto1 patients than the ones described so far, and it seems worthwhile to include Mto1 mutations in the differential diagnosis of hereditary cardiomyopathies and arrhythmias." (PMID 25506927, 2014).
bladder carcinoma (1 paper, 2021). "circRNA MTO1 has been shown to inhibit the progression of HCC, while circRNA cTFRC has been shown to promote bladder carcinoma progression by acting as a sponge for miR-107." (PMID 33858418, 2021).
cholelithiasis (1 paper, 2025). The presence of crystallized deposits forming in the gallbladder or biliary tree, primarily composed of cholesterol, bilirubin, and bile. "Specifically, the expression of the following genes was associated with a decreased risk of cholelithiasis: HEBP1 (OR = 0.92, 95% CI = 0.89–0.96) and MTO1 (OR = 0.94, 95% CI = 0.91–0.97), suggesting that these genes may be related to a reduced risk of cholelithiasis." (PMID 40958306, 2025).
gallbladder cancer (1 paper, 2021). "Such as, circular RNA circ-MTO1 expression is upregulated in GBC tissues and serves as a novel potential diagnostic and prognostic biomarker for gallbladder cancer." (PMID 34789260, 2021).
gastric tumor (1 paper, 2022). "According to the median of circ‐MTO1 expression in gastric tumor tissues, tumor circ‐MTO1 expression was divided by high (over 0.403) and low (below 0.403) expressions." (PMID 35478417, 2022). "Circ‐MTO1 was insufficiently expressed in gastric tumor tissue (median (interquartile range): 0.403 (0.288‒0.518)) compared with adjacent tissue (median (interquartile range): 1.000 (0.715‒1.524)) (p < 0.001)." (PMID 35478417, 2022).
glioblastoma (1 paper, 2022). The most malignant astrocytic tumor (WHO grade IV). "Circ-MTO1 expression was significantly decreased in glioblastoma tumors compared to neighboring normal tissues." (PMID 35883576, 2022). "In glioblastoma, a lower circ-MTO1 level was substantially related to shorter overall survival." (PMID 35883576, 2022). "Circ-MTO1 suppresses glioblastoma cell growth via the miR-92/WWOX signaling pathway." (PMID 35883576, 2022).
hepatopathy (1 paper, 2018). "While TRMU mutations may result in severe infantile hepatopathy or renal failure neither hepatopathy nor renal pathology are common features in MTO1 deficiency with each observed in fewer than 10% of cases." (PMID 29331171, 2018).
lymph node metastasis (1 paper, 2022). "Besides, tumor circ‐MTO1 was correlated with less lymph node metastasis (p = 0.014) and low TNM stage (p = 0.039), while was not correlated with demographic features or other clinical characteristics (all p > 0.05)." (PMID 35478417, 2022).
renal carcinoma (1 paper, 2022). A carcinoma arising from the epithelium of the renal parenchyma or the renal pelvis. "In fact, circ-MTO1 overexpression suppresses cell proliferation and metastases in both A497 and 786-O renal cancer cells, while silencing circ-MTO1 promotes proliferation of SN12C and OS-RC-2 renal cancer cells." (PMID 35813211, 2022).
tumor (12 papers, 2019 to 2024). "CircMTO1 originates from MTO1 (mitochondrial tRNA translation optimization 1 gene, hsa_circ_0007874), which is recognized as the tumor suppressor of HCC." (PMID 37371520, 2023). "The median (IQR) value of circ‐MTO1 expression in tumor tissue was 0.403 (0.288–0.518), while that in adjacent tissue was 1.000 (0.715–1.524)." (PMID 35478417, 2022). "Recently, cMTO1 (a circRNA derived from MTO1 (mitochondrial tRNA translation optimization 1) gene, hsa_circ_0007874) has been demonstrated to be a tumor suppressor in HCC." (PMID 32850833, 2020). "The higher expression of circ-MTO1 in tumor tissue compared to normal tissues suggests a better prognosis." (PMID 32904490, 2020). "Circ‐MTO1 is clinically correlated with tumor characteristics." (PMID 35478417, 2022). "Furthermore, tumor circ‐MTO1 high expression was independently correlated with prolonged disease‐free survival (DFS) (p = 0.013, adjusted hazard ratio (95% confidential interval): 0.314 (0.126‒0.782)), but was not correlated with overall survival (p > 0.05)." (PMID 35478417, 2022). "In addition, by promoting circRNAs, such as circ-MTO1, that can suppress tumor growth and metastasis, tumor growth can also be controlled." (PMID 35813211, 2022). "The fact that some of these EV proteins (e.g., PBIP1 and APOC2), mRNAs (e.g., DLC1 and MTO1), and miRNA (e.g., hsa-miR-99a-5p and hsa-mir-203a-3p) are present in the EVs of EC or SI tumor patients, exclusively, suggests that they are able to fulfill that unique role." (PMID 36568159, 2022). "The association between SNAI2 and the S2 (P1) or S3 (P2/P3) region of the MTO1 promoter was verified using the ChIP assay and further confirmed by a luciferase reporter gene assay in human granulosa-like tumor cells." (PMID 34413875, 2021). "CircMTO1 (hsa_circ_0007874) is derived from circularized exons 2–3 of mitochondrial tRNA translation optimization 1 (MTO1) gene and plays a dual role as a carcinogenic driver or tumor suppressor in cancer." (PMID 38671354, 2024). "Our results also suggested that the level of MTO1 mRNA, but not its circular form (circRNA), in human granulosa-like tumor cells was significantly decreased by RNase R treatment (Figures 1C1,C2)." (PMID 34413875, 2021).
mitochondrial disease (7 papers, 2013 to 2025). "In summary, the mitochondrial disease knowledgebase is expanded with this report on the largest cohort of MTO1 deficient patients to date and discussion about the phenotype (clinical and biochemical), genotype, natural history, outcomes and treatments." (PMID 29331171, 2018). "The aim of this study was to review and report on 35 cases of MTO1-deficient mitochondrial disease, outlining their clinical and molecular features, response to treatment and genotype-phenotype evaluation." (PMID 29331171, 2018). "Loss of taurine modifications caused by mutations in MTO1, GTPBP3, mt-tRNALeu(UUR), or mt-tRNALys genes causes various mitochondrial diseases, which will be described in a later section." (PMID 39719325, 2025). "As is observed with other nuclear-mitochondrial diseases of mt-tRNA modification such as TRIT1, TRMT5, GTPBP3 and PUS1, MTO1 deficiency usually results in a combined reduction of mtDNA-dependent respiratory chain activities." (PMID 29331171, 2018).
cancer (4 papers, 2013 to 2024). A tumor composed of atypical neoplastic, often pleomorphic cells that invade other tissues. "As for prognosis of cancer patients, circ‐MTO1 is associated with their better survivals." (PMID 35478417, 2022). "Circ‐MTO1 is one of the commonly studied circRNAs, which acts as a cancer‐suppressor gene involved in a variety of cancers." (PMID 35478417, 2022). "Methylation level was inversely correlated with expression level; MTO1 showed higher CpG methylation but lower expression in ER + cancer tissues than in the ER- cancer tissues." (PMID 24160266, 2013). "MTO1 was upregulated in ER- cancer types, meanwhile MRPL41 was upregulated in ER+ cancer types, showing an inverse correlation between expression and promoter methylation." (PMID 24160266, 2013). "However, the results revealed no statistically significant expression difference between cancer tissues and normal tissues for both MTO1 and MRPL41." (PMID 24160266, 2013).
myopathy (3 papers, 2014 to 2023). A disease of the muscle in which the muscle fibers do not function properly. "According to a recent retrospective analysis of 35 patients carrying a MTO1 mutation, a small number of patients with myopathy of the skeletal muscles has been reported." (PMID 32316520, 2020).
MTO1 also shares sentences with these, for which no sentence is quoted: infantile hypertrophic cardiomyopathy (5 papers); Mitochondrial myopathy (3); liver failure (2); Alstrom syndrome (1); Ataxia (1); brain disorder (1); Cognitive impairment (1); Desminopathy (1); developmental delay (1); Encephalopathy (1); endometrial cancer (1); Failure to thrive (1); glioma (1); hereditary cardiomyopathies (1); Hyperhomocystinemia (1); infantile spasms (1); Intellectual disability (1); lung carcinoma (1); maple syrup urine disease (1); MERRF (1); metabolic myopathy (1); mitochondrial encephalomyopathy (1); myocardial hypertrophy (1); nonsyndromic deafness (1); optic atrophy (1); renal cell carcinoma (1); renal failure (1); sideroblastic anaemia (1); Stroke (1); vitamin B12 deficiency (1).